MTOR (mechanistic target of rapamycin kinase)
Diseases named in the same sentence as MTOR in open-access papers (continued):
Sharing a sentence is not in itself a finding about the gene and the disease.
leukemia (continued). "The primary objective of this phase I single center open label study was to determine the maximum tolerated dose (MTD) and recommended phase II dose (RP2D) of the dual pan-class I PI3K and mTOR inhibitor BEZ235 in patients with advanced leukemia." (PMID 32993794, 2020). "Of particular note, we identified RNF126 as a novel E3 ligase for mTOR in NTS-treated leukemia cells." (PMID 32131492, 2020). "The aberrant activation of the PI3K/AKT/mTOR pathway is one of the most common biochemical features of leukemia." (PMID 32425881, 2020). "Our preliminary investigations suggest that CDK8 interacts with the mTOR signaling pathway not only in a subset of leukemia patients but also in a range of solid cancers." (PMID 31628323, 2019). "For example, in a mouse model of human acute myeloid leukemia (AML), Gnetin-C showed powerful anti-leukemia properties via inhibition of mTOR and MAPK kinases, two pathways that are aberrantly activated in AML cells." (PMID 31234376, 2019). "The PI3K/mammalian target of rapamycin (mTOR) pathway is one of the most frequently deregulated pathways in leukemia." (PMID 30925702, 2019). "The key role of mTOR in the early stages of leukemia and cell drug resistance has been documented in many scientific works." (PMID 30795552, 2019). "Recent study indicated that 4‐O‐methyl‐ascochlorin induced the human leukemia cells by suppressing c‐Myc protein synthesis via an AMPK/mTOR‐dependent mechanism." (PMID 30918653, 2019). "The dual inhibitor PI3K/mTOR inhibitor PKI-587 (Gedatolisib) exhibited a significant inhibitory effect on T-ALL leukemia cells and in T-ALL patients with poor prognosis." (PMID 30795552, 2019). "Amino-functionalized polystyrene nanoparticle treatment initiates G2 cell cycle arrest and blocks proliferation and vascularization in leukemia cell lines through the inhibition of mTOR signaling pathways." (PMID 30642006, 2019). "For instance, amino-decorated NPs steadily inhibited mTOR activity and proliferation in three leukemia cell lines." (PMID 30642006, 2019). "For example, rapamycin, an inhibitor of mTOR signaling pathway, can eliminate CSCs of PTEN-deficient leukemia." (PMID 30310855, 2018). "The PI3K/Akt/mTOR signaling pathway is often activated in leukemia and is involved in leukemogenesis." (PMID 29642462, 2018). "The critical role of mTOR in leukemia initiation, progression, and chemoresistance has also been proven by scientific and clinical studies evaluating its down-modulation." (PMID 30110936, 2018). "In summary, our findings indicate that the combined inhibition of the JAK/STAT and mTOR pathways by novel more potent inhibitors can effectively inhibit cell signaling and reduce leukemia burden in CRFL2-re Ph-like B-ALL cell lines and PDX models." (PMID 29487712, 2018). "Alterations of the PI3K/AKT/mTOR pathway are predominant in T-ALL (85% of cases) with respect to other leukemia types including B-ALL." (PMID 29642462, 2018). "Particularly, mTOR constitutive activation is frequently found in leukemia patients, contributing to chemoresistance, disease progression, and unfavorable outcomes." (PMID 30110936, 2018). "Results from our current study are concordant with the recently reported combination effect of TKIs with mTOR inhibitors to enhance anti-leukemia potential." (PMID 29464092, 2018). "The role of the PI3K/Akt/mTOR pathway in leukemias has been widely studied, both for in vitro and in vivo models, in order to explore the therapeutic perspective of its inhibition." (PMID 30110936, 2018). "Torkinibs, ATP-competitive inhibitors of the mTOR kinase activity, target both mTOR complexes and have already displayed promising anti-cancer properties on leukemia models." (PMID 30147674, 2018). "At the molecular level, an IGF1-IGF-1R autocrine loop is responsible for activation of a leukemia-supportive PI3K/Akt/mTOR pathway." (PMID 30147674, 2018).
leukemia (continued). "Subsequently, simultaneous blockade of PI3K/mTOR and the Bcl-2 pathway was shown to have promising antileukemic activity in leukemia cell lines, primary samples, and xenograft models." (PMID 30110936, 2018). "For instance, BCAT1 exerts its oncogenic function through BCAA production of leukemia by activating mTOR signaling." (PMID 29802157, 2018). "Lastly, from a clinical/translational perspective, we recapitulate the therapeutic results in leukemia, obtained by using mTOR inhibitors as single agents and in combination with other compounds." (PMID 30110936, 2018). "We next analyzed the signaling perturbations by JAK2 and mTOR inhibitors in the leukemia cells (gated on hCD19 by flow cytometry) collected from the murine spleens." (PMID 29487712, 2018). "Inhibitors of the PI3K/AKT/mTOR pathway have been shown to elicit anti-leukemia activity in cultured AML cells." (PMID 29254232, 2017). "A previous study has reported that inhibition of mTOR prevents the migration and invasion of leukemia cells through the inhibition of STAT3 phosphorylation." (PMID 29212252, 2017). "Increased activity of the PI3K/Akt/mTOR pathway has been proposed as an escape route for TKI resistance in BCR-ABL1-positive leukemias and combining nilotinib with dual PI3K/mTOR inhibitor has been shown to have a synergistic effect." (PMID 28186983, 2017). "Genetic mutations, over-activated tyrosine kinase receptors, and amplification of key factors in PI3K/AKT pathways have been identified to lead to abnormal activation of mTOR signaling in leukemia." (PMID 28186963, 2017). "Aberrant expression or activation of mediators such as osteopontin (OPN) or PI3K/PTEN/Akt/mTOR pathway plays a key role in making prone to develop leukemia." (PMID 28875010, 2017). "To further confirm our initial findings from the cell line models on primary cells, we tested eight T-cell LGL-leukemia patient samples against mTOR, Hsp90 and JAK inhibitors." (PMID 29228628, 2017). "The deletion of phosphatase and tensin homologue (PTEN), which negatively regulates the PI3K/Akt/mTOR pathway, leads to leukemia, including AML in mice." (PMID 27071307, 2016). "Taken together, these results reveal an unrecognized function of MTE in inhibiting the proliferation and inducing the apoptosis of T-ALL cells, and identify a pathway of PTEN/PI3K/AKT/mTOR for the effects of MTE on leukemia therapy." (PMID 27756877, 2016). "Latrophilin-1 is functional in leukaemia cells tested, and its biosynthesis is controlled through the mammalian target of rapamycin (mTOR), a master regulator of myeloid cell translational pathways." (PMID 27322212, 2016). "Their ability to hamper T cell function together with their potential anti-leukemia effect turn the use of drugs that target PI3K/AKT/mTOR pathway into a promising approach in the context of allo-HSCT." (PMID 27765055, 2016). "The PI3K/Akt/mTOR signaling pathway is often activated in leukemias and plays a crucial role in leukemogenesis." (PMID 27821800, 2016). "This study thus not only identifies MTE's unrecognized function in anti-T-ALL cells, but also reveals a novel pathway PTEN/PI3K/AKT/mTOR for the effects of MTE on leukemia therapy." (PMID 27756877, 2016). "Treatment of all these leukaemia cells with the inflammatory mediator lipopolysaccharide (LPS) further upregulates LPHN1 translation via mammalian target of rapamycin (mTOR, a master regulator of myeloid cell translation and growth)." (PMID 27322212, 2016). "In this study, we have measured the phosphorylation status of mTOR pathway molecules in leukaemia cells in conjunction with their proliferation status." (PMID 26985829, 2016).
leukemia (continued). "We show that FK866 induces a translational arrest in leukemia cells through inhibition of MTOR/4EBP1 signaling and of the initiation factors EIF4E and EIF2A." (PMID 26542945, 2015). "Recently, it has been demonstrated that exposure of human leukemia HL-60 cells to fascaplysin leads to an inhibition of all major proteins of the PI3K/AKT/mTOR pathway." (PMID 26569265, 2015). "Among the survival signals, PI3K/Akt/mTOR pathway had been reported to be playing a critical role in the pathogenesis progression of leukemia." (PMID 26436418, 2015). "Thymic stromal-derived lymphopoietin (TSLP), the ligand binding to CRLF2, induces leukemia proliferation involving mTOR signaling and cases of Ph-like ALL with aberrant CRLF2 expression displayed increased mTOR signaling activity." (PMID 25682198, 2015). "Previous studies have shown that inhibition of the MTOR/4EBP1 pathway in leukemia cells leads to a reduction in the levels of the anti-apoptotic protein MCL1, with important implications for chemosensitivity." (PMID 26542945, 2015). "Co-administration of HDAC inhibitors with perifosine (an Akt inhibitor) and rapamycin (an mTOR inhibitor) in human leukemia cells also promotes mitochondria injury and apoptosis." (PMID 25669976, 2015). "Taken together, we provide functional evidence that the TTLshort/early relapse ALL is characterized by highly activated mTOR signaling driving in vivo leukemia growth." (PMID 25682198, 2015). "By analysis of S6-phosphorylation downstream of mTOR, increased mTOR activation was found in TTLshort/high-risk ALL, which was effectively abrogated by mTOR inhibitors resulting in decreased leukemia proliferation and growth." (PMID 25682198, 2015). "Inhibition of mTOR signaling resulted in decreased cellular proliferation in vitro, and importantly also in patient-derived leukemias upon in vivo therapy." (PMID 25682198, 2015). "A number of pan-class I PI3K and dual class I/mTOR inhibitors are now in clinical trials for cancer, including leukaemia." (PMID 26442967, 2015). "Given our findings of hyperactivated mTOR signaling and susceptibility for pathway inhibition in TTLshort ALL, we next analyzed effects and mechanisms of mTOR inhibition in TTLshort leukemia." (PMID 25682198, 2015). "PP242 and its clinical analogue INK128 have been shown to effectively shut down mTOR signalling, and as a result, destroy leukaemia cells dependent on this pathway." (PMID 25392452, 2014). "ATP-competitive “active-site” mTOR inhibitors produce more complete mTOR inhibition and are more effective than rapamycin in preclinical models of leukemia, lymphoma and multiple myeloma." (PMID 24586420, 2014). "Consistently, PS-NH2 inhibits the activation of the mTOR downstream targets, Akt and p70 ribosomal S6 kinase 1, and blocked proliferation in three leukemia cell lines in vitro and in vivo." (PMID 25671136, 2014). "In a mouse leukemia model with deletion of Pten, which acts upstream of mTOR and attenuates the PI3K/Akt/mTOR signal, rapamycin not only depleted leukemia-initiating cells but also restored normal hematopoietic stem cell function." (PMID 24231729, 2013). "We cultured leukaemia cells continuously in vitro in the presence of an mTOR inhibitor to model dormancy." (PMID 23767415, 2013). "Leukemia cell lines exhibited increased mTOR activity, indicated by phospho-S6 ribosomal protein (p-S6) and phosphorylated eukaryotic initiation factor 4E binding protein (p-4EBP1)." (PMID 23573198, 2013). "In the present study, the amount of mTOR activity dependent phospho-proteins was characterized by ELISA in human leukemia cell lines and in lymphoblasts from childhood ALL patients (n = 49)." (PMID 23573198, 2013). "An alternative approach to potentiate the cytotoxic effects of glycolysis inhibitors in leukemia is the targeting of the mammalian target of rapamycin (mTOR) pathway, which is critical for cellular responses to metabolic stress." (PMID 24024216, 2013).
leukemia (continued). "Ultimately, our results suggest that inhibition of IGF1R-Akt-mTOR signaling plays a key role in the cytotoxic effect of shikonin against U937 leukemia cells." (PMID 23861714, 2013). "The Ras/Raf/MEK/ERK, PI3K/PTEN/Akt/mTOR, Wnt/beta-catenin, Notch, Hedgehog and other pathways are being shown to play key roles in cancer initiating cells (CICs) and leukemia initiating cells (LIC)." (PMID 23455493, 2012). "The effects of targeting different levels of the PI3K/PTEN/Akt/mTOR pathway has also been examined in various leukemias." (PMID 23455493, 2012). "Preclinical data also suggest that allosteric mTOR inhibition with rapamycin impaired leukemia initiating cells (LICs) function." (PMID 23271044, 2012). "On the basis of these observations, we established a murine AML model with high Evi1 expression by BM transplantation and aimed to test the efficacy of the mTOR inhibitor rapamycin on the leukemia model in vivo." (PMID 21795762, 2011). "Extensive studies regarding PI3K/AKT/mTOR signaling and leukemia have demonstrated that PI3K/AKT signaling is frequently activated in AML." (PMID 21795762, 2011). "It is reported that the proliferation and apoptotic resistance of leukemia cells was closely related to several oncogenic signaling pathways such as Akt/mTOR, Stat3 and ERK." (PMID 19897545, 2011). "Among these, compound 9a (LASSBio-2337) emerged as a dual pan-PI3K/mTOR inhibitor (IC50: 0.3-5.8 μM), showing cytotoxic effects in leukemia cell lines (CC50: 4.37-9.44 μM), including those with multidrug resistance (Lucena, MDR phenotype), while sparing nontumor hPBMCs." (PMID 41726721, 2026). "RNA sequencing (RNA-seq) and quantitative PCR (qPCR) analyses of the xenograft tumors confirmed the expression of mTOR-regulated genes in primary CRLF2 B-ALL cells, substantiating the involvement of the PI3K/mTOR pathway in TSLP/TSLPR-mediated leukemia proliferation." (PMID 40787610, 2025). "Furthermore, the application of NPs to prevent leukemia and cytotoxicity was evaluated by following the phosphatidylinositol 3-kinase/protein kinase B/mammalian target of rapamycin (PI3K/AKT/mTOR) signaling pathway." (PMID 41041347, 2025). "Propofol triggered Akt/mTOR, which prevented leukemia stem cells from maintaining self-renewing." (PMID 41233892, 2025). "Given the pivotal roles of these pathways, developing and testing dual inhibitors targeting both the Hh and PI3K/Akt/mTOR pathways offers a promising future strategy for overcoming therapy resistance and improving treatment outcomes in leukemia and other cancers." (PMID 39996741, 2025). "The mTOR pathway is involved in the development of leukemia in two ways: first, it prevents leukemia cells from becoming normal blood cells by preventing cell differentiation; second, it encourages protein synthesis and cell growth, which keeps leukemia cells alive and enables them to proliferate." (PMID 41451233, 2025). "However, NK cell metabolic and functional failure results from chronic cytokine stimulation, particularly IL-15/mTOR signaling, in mice models of leukemia." (PMID 41451233, 2025). "Inhibitors of mTOR have been demonstrated to have anti-leukaemia activity in AML54–56." (PMID 40425534, 2025). "Key phosphoproteins in AMPK/PI3K/mTOR signaling were stimulated by stroma-dependent protection with HDACi treatment of leukemia for which its protein network kinase activities have been previously shown to protect leukemia cells by suppressing oxidative stress in the bone marrow microenvironment." (PMID 38851813, 2024). "Furthermore, mTOR inhibitors Everolimus and Temsirolimus have shown promising results as adjunctive agents together with traditional drug therapy against leukemia in various settings in preclinical and early phase clinical trials." (PMID 38159164, 2024). "The PI3K/Akt/mTOR pathway plays a crucial role in cancer, including leukemia." (PMID 37958470, 2023). "GAS5 can increase the resistance of mammalian targeted rapamycin (mTOR) antagonists in leukemia." (PMID 37993867, 2023).
leukemia (continued). "Using KEGG enrichment analysis to identify the ten most enriched metabolic pathways, we found that the leukaemia cell lines (Jurkat and K562) were highly enriched in oxidative phosphorylation, mTOR signalling, RNA degradation and regulation of cancer-related metabolic pathways." (PMID 37274234, 2023). "Therefore, inhibiting PI3K/Akt/mTOR signaling represents a significant therapeutic target for leukemia treatment." (PMID 36145344, 2022). "Inducing the phosphorylation of AMPK or inhibiting the mTOR activity in leukemia cells may be a potential method for acute leukemia treatment." (PMID 36148953, 2022). "Importantly, the mTOR pathway inhibitor rapamycin shows a synergistic effect with ATO in the induction of NETosis-mediated elimination of leukemia-initiating cells (LICs) in APL cells and in an APL model in vivo." (PMID 35526025, 2022). "In our study, GO analysis of leukaemia cells revealed that PI3K/AKT pathway was activated in leukaemia cells co-cultured with T-ALL derived MSCs and the protein expression level of p-PI3K, p-AKT, p-mTOR in leukaemia cells were also increased after co-culture with T-ALL derived MSCs." (PMID 36333298, 2022). "Interestingly, the AKT/mTOR pathway is dysregulated and hyperactive in 50–80% of human leukemia cases." (PMID 35250566, 2022). "In addition, previous studies have found that matrine can inhibit the progression of leukemia through Akt/mTOR and other signaling pathways, but here we have found a more critical target and mechanism of matrine." (PMID 36339620, 2022). "Therefore, proteins involved in JAK/STAT and PI3K/Akt/mTOR pathways provide vital targets for treating leukemia." (PMID 36145344, 2022). "In addition, TQ inhibits PI3K/Akt/mTOR and JAK/STAT signaling in myeloid leukemia cells, which was associated with growth inhibition of leukemia cells." (PMID 36145344, 2022). "However, after addition of BGJ398 or FGF2 knockdown, the expression of phosphorylation of PI3K/AKT/mTOR proteins were significantly reduced, indicating that FGF2/FGFR2 combination activated PI3K/AKT/mTOR pathway in leukaemia cells." (PMID 36333298, 2022). "It is important to note that ATM-mediated regulation of mTOR protein levels does not appear to be unique to FLT3-dependent AMLs or leukemia in general, as implicated with our analyses of other cell types." (PMID 36259537, 2022). "We thus hypothesized that GPR132 activation by 8GL may downregulate mTOR activity by stimulating the Gαs-cAMP-PKA pathway in leukemia." (PMID 36437247, 2022). "The apoptosis in treated cells suggests that USP30 inhibitors combined with AKT/mTOR inhibitors might prove a benefit in treating leukemia." (PMID 35250566, 2022). "Moreover, TQ induced inhibition of PI3K/Akt/mTOR and JAK/STAT signaling pathways, which was associated with inhibition of proliferation of the leukemia cells." (PMID 36145344, 2022). "RNA sequence results revealed that T-ALL derived MSCs secreted fibroblast growth factor 2 (FGF2), which combined with fibroblast growth factor receptor 2 (FGFR2) on leukaemia cells, resulting in activation of PI3K/AKT/mTOR signalling pathway in leukaemia cells." (PMID 36333298, 2022). "mTOR inhibition has been shown to be chemoprotective in leukemia cells." (PMID 36396656, 2022). "We next asked whether USP30 could be a viable target to synergize with AKT/mTOR inhibitors for leukemia treatment." (PMID 35250566, 2022). "It has been shown that c-Myc expression is down-regulated by the AMPK/mTOR pathway, both in pancreatic tumor cells and in leukemia cells; therefore, we investigated whether phenformin also controls c-Myc expression through the mTOR pathway in keratinocytes." (PMID 35954273, 2022). "Interestingly, the feeding of leukemia stem cells with specific dipeptides affects mTOR activity and nutrient signaling." (PMID 35003157, 2021).